USP7 (ubiquitin specific peptidase 7)
Diseases named in the same sentence as USP7 in open-access papers (continued):
Sharing a sentence is not in itself a finding about the gene and the disease.
hepatocellular carcinoma (39 papers, 2015 to 2025). A malignant tumor that arises from hepatocytes. "For example, exo-circRNA from adipocytes promotes the growth of hepatocellular carcinoma by targeting deubiquitination associated USP7." (PMID 39484707, 2024). "In hepatocellular carcinoma (HCC), USP7 overexpression is significantly associated with malignant phenotypes such as tumor enlargement, poor differentiation, and microvascular invasion." (PMID 39767641, 2024). "Exosome circRNA from adipocytes accelerated the growth of hepatocellular carcinoma via targeting deubiquitination-related USP7." (PMID 33425899, 2020). "Adipocyte exosomes have also been reported to promote the growth of hepatocellular carcinoma by targeting deubiquitination-related USP7 and promote melanoma aggressiveness through fatty acid oxidation." (PMID 30971292, 2019). "For example, overexpression of USP7 deubiquitinase promotes hepatocellular carcinoma (HCC) progression, and USP2a overexpression is detected in aggressive human PCa specimens." (PMID 25734985, 2015). "METTL3 could also drive hepatocellular carcinoma progression by mediating m6A modification of ubiquitin-specific processing protease 7 (USP7) or abnormal spindle-like microcephaly (ASPM)." (PMID 36476503, 2022). "It regulates the growth of hepatoma cells through the circ-DB/miR-34a/USP7/cyclin A2 pathway." (PMID 33627631, 2021). "METTL3 was highly expressed in hepatocellular carcinoma (HCC), and the expression of ubiquitin-specific protease (USP7) was also increased." (PMID 36835633, 2023). "USP7 was significantly increased in hepatocellular carcinoma (HCC) and inhibition of USP7 efficiently suppressed tumor growth." (PMID 36474192, 2022). "In addition, METTL3 may regulate the expression of USP7 through modification of m6A methylation and may promote the invasion of hepatocellular carcinoma cells." (PMID 36230944, 2022). "USP7 depletion in hepatocellular carcinoma (HCC) cell lines decreases proliferation and increases the number of cells arrested at the G1 stage." (PMID 32759846, 2020). "Unsurprisingly, overexpression of USP7 and TRIP12 has been found to be associated with poor prognosis in cancers with aberrant expression of p14ARF, such as hepatocellular carcinoma (HCC)." (PMID 29858610, 2018). "USP7 accelerates p14(ARF) degradation by deubiquitinating thyroid hormone receptor-interacting protein 12 and promotes hepatocellular carcinoma progression." (PMID 40389405, 2025). "Some studies have shown that USP7 is a key effector protein in the emergence of DOX chemoresistance in neuroblastoma, hepatocellular carcinoma and pancreatic cancer, and USP7 inhibition can significantly increase the chemosensitivity of tumors." (PMID 33967786, 2021). "To understand the regulatory relationship between USP7 and ZNF638, we inhibited the activity of USP7 in the SK-Hep1 or Huh-7 hepatoma cell line by addition of pharmacological inhibitor P22077 and then observe the protein level of ZNF638." (PMID 33040080, 2020). "Finally, in hepatocellular carcinoma (HCC), USP7 seems to increase the expression of the Tripartite Motif Containing 27 (TRIM27) gene by enhancing its stability through deubiqutination." (PMID 41157055, 2025). "METTL3 and ubiquitin specific peptidase 7 (USP7) expressions were interrelated in hepatocellular carcinoma cells and conclusive remarks obtained were that maybe METTL3 can regulate the USP7 expression by m6A methylation." (PMID 39691424, 2024). "Furthermore, in hepatocellular carcinoma (HCC), the adapter protein PROX1 can promote NF-κB signaling by recruiting USP7 to the p65-p50 complex and facilitating p65 deubiquitination." (PMID 39767641, 2024).
hepatocellular carcinoma (continued). "The TRIP12 result is consistent with previous reports that showed that knockdown of TRIP12 by shRNA does not affect USP7 levels in hepatocellular carcinoma cells." (PMID 30367141, 2018). "The study shows that RPAP2, acting as an oncoprotein, promotes hepatocellular carcinoma (HCC) progression, with its stability being negatively regulated by FBXW7, yet positively by HSP90 and USP7." (PMID 39932049, 2025).
gastric cancer (31 papers, 2018 to 2025). A primary or metastatic malignant neoplasm involving the stomach. "As a deubiquitinase, ubiquitin-specific protease 7 (USP7) plays a vital role in diverse cancers, nevertheless, its role in gastric cancer (GC), which is the fifth leading cause of death in diverse cancers worldwide, has rarely been reported." (PMID 40061891, 2025). "One study revealed that PD-L1 expression was positively associated with USP7 levels in gastric cancer patients." (PMID 37215134, 2023). "For instance, USP7 has been shown to suppress ferroptosis by activating stearoyl-CoA desaturase in gastric cancer, whereas USP8 knockdown enhanced ferroptosis through inhibiting GPX4 in CRC." (PMID 40962058, 2025). "USP7 inhibition sensitized gastric cancer cells to T cell-mediated killing by increasing PD-L1 polyubiquitination and decreasing PD-1/PD-L1 interaction." (PMID 41157055, 2025). "In gastric cancer, USP7 is involved in ferroptosis, a programmed cell death mechanism induced by iron-depended lipid-reactive oxygen species." (PMID 41157055, 2025). "Mechanistically, in gastric cancer cells, USP7 interacts with PD-L1 to remove its ubiquitin chains, stabilizing PD-L1." (PMID 39223632, 2024). "Analyzing data from TCGA and tissues, a direct correlation between PD-L1 and USP7 expressions was found in gastric cancer." (PMID 38638430, 2024). "DHPO can inhibit USP7 activity to induce ferroptosis, preventing the invasion and migration of gastric cancer cells." (PMID 39396974, 2024). "USP7 was reported to regulate PD-L1 stability and modulate sensitization of gastric cancer cells to T cells killing." (PMID 38638430, 2024). "USP7 stabilize hnRNPA1 through transferring miR-522 to increase gastric cancer cells’ resistance to cisplatin treatment." (PMID 39605891, 2024). "Although USP7, hnRNPA1 and miR-522 are proved to be up-regulated in gastric cancer, they are also widely expressed in normal tissues." (PMID 32106859, 2020). "To gain a more complete profile of USP7 interactions in cancer cells, we performed affinity purification coupled to mass spectrometry to identify USP7 binding targets in gastric carcinoma cells." (PMID 30367141, 2018). "Here we use affinity purification coupled to mass spectrometry (AP-MS) to identify USP7 interactions in gastric carcinoma cells." (PMID 30367141, 2018). "Here we use a proteomics approach to further identify specific USP7 targets in the context of gastric carcinoma cells." (PMID 30367141, 2018). "In addition, DHPO has been identified as a potent USP7 inhibitor, which has been found to induce ferroptosis in gastric cancer cells by targeting the deubiquitination of Stearoyl-CoA Desaturase mediated by USP7." (PMID 40136417, 2025). "However, only 287 pairs of gastric cancer tissues and adjacent normal tissues were used in this study, and only the correlation between USP7 expression and age, gender, lymph node metastasis, and degree of differentiation was analyzed." (PMID 40061891, 2025). "Moreover, in gastric cancer, USP7-mediated deubiquitination is responsible for the interaction and stabilization of PD-L1, and the expression of the two proteins seems to be positively correlated." (PMID 41157055, 2025). "USP7 modulates sensitization of gastric cancer cells to T cells killing." (PMID 38638430, 2024). "Inhibiting USP7 activity enhances T cell killing of gastric cancer cells." (PMID 39223632, 2024).
gastric cancer (continued). "Currently, it was well documented that hnRNPA1 could be recruited by USP7 to facilitate exo-lncFERO and exo-miR-522 secretion, aiding their regulating of lipid metabolism, ferroptosis and individual chemosensitivity gastric cancer (GC) cells." (PMID 35879279, 2022). "Hence, the expression of USP7 in seven gastric cancer cell lines was investigated." (PMID 40061891, 2025). "One study reported that USP7 expression is positively related to PD-L1 expression and USP7 directly binds to PD-L1 which stabilized it in gastric cancer.However, the function of USP7 inhibitors in enhancing the immune response in bladder cancer remains unclear." (PMID 37497216, 2023). "Hence, USP7 suppression by its inhibitors not only blocked gastric tumor cell proliferation but also inhibit the expression of PD-L1 to improve anti-cancer immune response in gastric cancer." (PMID 37215134, 2023). "In turn, the circular RNA derived from ribosomal protein S19 (circRPS19) upregulates USP7 expression, leading to an increase in HK2 protein levels and the promotion of aerobic glycolysis in gastric cancer cells." (PMID 39048965, 2024). "Previous studies demonstrated that USP7, USP9X and USP22 stabilize PD-L1 in gastric cancer, oral squamous cell carcinoma or liver cancer, respectively." (PMID 38167274, 2024). "A novel Ubiquitin‐Specific Protease 7 (USP7) inhibitor, DHPO, is identified through in silico screening for gastric cancer (GC) treatment." (PMID 38460164, 2024). "In gastric cancer, depletion of USP7 by p5091 decreased PD-L1 (Programmed Cell Death 1 Ligand 1, also known as CD274) expression and sensitized gastric cancer cells to T cell killing." (PMID 35307036, 2022). "In a nutshell, pharmacological and genetic abrogation of USP7 can inhibit the proliferation of MKN45 cells both in vitro and in vivo, which indicates that USP7 can be considered as a promising therapeutic target for the treatment of gastric cancer." (PMID 40061891, 2025). "To characterize new functions of USP7 through the identification of novel interactors, we performed affinity purification coupled to mass spectrometry (AP-MS) on FLAG-tagged USP7 that was expressed in AGS gastric carcinoma cells." (PMID 30804394, 2019). "It has been reported that both USP7 and USP22 protect PD-L1 from ubiquitination-mediated degradation in cancers including gastric cancer, lung adenocarcinoma, and liver cancer, neither of which was enriched in our screening." (PMID 38038129, 2023).
colon carcinoma (29 papers, 2015 to 2025). "In both tissue culture and tumor xenograft models, USP7 knockdown improved the susceptibility of colon cancer cells to histone deacetylase 1 (HDAC) inhibitors." (PMID 36428632, 2022). "USP7 is also implicated in modulating tumor growth and apoptosis in a colon carcinoma xenograft model." (PMID 27780924, 2016). "Of note, USP7 knockdown in colon cancer organoids significantly reduced the growth rate of the organoids." (PMID 39840939, 2025). "The observed reversion of colon cancer organoids to a more normal state upon USP7 inhibition supports the predictions made by our mechanistic Boolean network models and attractor landscape analysis." (PMID 39840939, 2025). "To investigate the efficacy of USP7 as a potential target for cancer reversion in colon cancer organoids, we conducted USP7 knockdown experiments using the inhibitor P22077 in colon cancer organoids previously used in the process of network reconstruction." (PMID 39840939, 2025). "Together, these findings indicate that knockdown of USP7 in colon cancer organoids can facilitate the reversion of them to more normal colon states." (PMID 39840939, 2025). "We observed that USP7 overexpression resulted in an increased radiosensitivity, which is in line with observations in colon carcinoma xenograft models, where USP7 overexpression led to an increased growth inhibition after irradiation." (PMID 38672118, 2024). "USP7 functions as a WNT activator through the deubiquitination of β-catenin and promotes the growth of APC-mutated colon cancer cells." (PMID 37740002, 2023). "For example, ZMIZ2 promoted tumour proliferation of colon cancer by recruiting USP7, deubiquitinating β‐catenin, and thereby activating WNT signalling pathway." (PMID 38073586, 2023). "In colon cancer, mutated APC promote β-catenin deubiquitination mediated by USP7, leading to the activation of Wnt signaling." (PMID 34577547, 2021). "For example, small‐molecule inhibitor P5091 inhibits USP7 in colon cancer and chronic leukemia, and small‐molecule inhibitor b‐AP15 plays a significant role in inhibiting the cell growth of leukemia and esophageal squamous cell carcinoma." (PMID 33619866, 2021). "The inhibition of USP7 by P5091 in colon cancer cells (HCT116, SW480 and Caco-2) stabilizes Wnt signaling activity through β-catenin degradation and suppresses colon cancer cell proliferation." (PMID 34577547, 2021). "Although this molecule has shown selectivity towards USP7 in HCT116 human colon cancer cells, its weak activity against other related proteases limits the use for further pre-clinical studies." (PMID 32531973, 2020). "Treatment with P5091 led to a significant and dose-dependent decrease in PE in the MDA-MB-231 WT and MCF7 cells, which is in line with observations in ovarian cancer cells, lung squamous cell carcinoma cells and colon carcinoma xenograft models after USP7 depletion or inhibition." (PMID 38672118, 2024). "In addition, USP7 deubiquitinates β-catenin and activate Wnt signaling to promote colon cancer development." (PMID 37081042, 2023).
colon carcinoma (continued). "More specifically, treatment with VP could effectively suppress the expression of USP7 and tumor growth, which should provide clinical benefit for the treatment of colon cancer." (PMID 34055773, 2021). "Verteporfin (VP) effectively inhibited the proliferation of colon cancer cells and organoids and could even modulate serine metabolism by inhibiting USP7 expression." (PMID 34055773, 2021). "It was reported that USP7 could activate Wnt signaling pathway and promote tumorigenesis by mediating β-catenin deubiquitination in adenomatous polyposis coli (APC) mutations from colon tumors." (PMID 34740372, 2021). "Recently, EZH2 was found to be a target substrate for USP7, and USP7 deubiquitinates and stabilizes EZH2 and promotes cell migration, invasion, and sphere-forming potential in prostate and colon cancer cells." (PMID 37762082, 2023). "A positive correlation between the expression of the deubiquitinating enzyme USP7, the YAP target gene CTGF, and the serine metabolic enzyme PHGDH was detected in colon cancer tissues." (PMID 34055773, 2021). "Clinically, YAP was significantly activated in colon tumor tissues and positively correlated with the expression of phosphoglycerate dehydrogenase (PHGDH) and USP7." (PMID 34055773, 2021). "To further explore the relationship between PHGDH, USP7, and CTGF, we evaluated the mRNA expression of PHGDH, USP7, and CTGF in tissues from 87 patients with colon cancer via qRT-PCR." (PMID 34055773, 2021). "In this study, we found that high concentrations of serine stabilized YAP; therefore, to gain insight into the regulatory mechanism, we focused on the relationship between USP7 and YAP in colon cancer models with abnormal serine metabolism." (PMID 34055773, 2021). "P5091 is reported to target USP7 and USP47 and act as an anti-cancer agent in MM and HCT116 colon cancer cells." (PMID 33158118, 2020). "Generally, our study uncovered the mechanism by which serine metabolism regulates YAP via USP7 and identified the crucial role of YAP in the regulation of cell proliferation and tumor growth; thus, VP may be a new treatment for colon cancer." (PMID 34055773, 2021). "Moreover, in colon cancer tissues from patients, YAP was positively related by PHGDH and USP7." (PMID 34055773, 2021).